PSMC2 (proteasome 26S subunit, ATPase 2)
Description:
Component of the 26S proteasome, a multiprotein complex involved in the ATP-dependent degradation of ubiquitinated proteins. This complex plays a key role in the maintenance of protein homeostasis by removing misfolded or damaged proteins, which could impair cellular functions, and by removing proteins whose functions are no longer required. Therefore, the proteasome participates in numerous cellular processes, including cell cycle progression, apoptosis, or DNA damage repair. PSMC2 belongs to the heterohexameric ring of AAA (ATPases associated with diverse cellular activities) proteins that unfolds ubiquitinated target proteins that are concurrently translocated into a proteolytic chamber and degraded into peptides.
Synonyms: MSS1; S7; Nbla10058; RPT1
Tractability: Small molecule: an approved drug acts on it; a structure with a bound ligand is known; a high-quality ligand is known. Antibody: its Gene Ontology location is reachable by antibodies, with high confidence. PROTAC: UniProt records ubiquitination sites on it; ubiquitination databases record sites on it; its protein half-life has been measured.
Target class: Enzyme
Gene: Protein-coding gene on chromosome 7 (103,328,570 to 103,370,346, forward strand). Ensembl gene ENSG00000161057.
Subcellular location: Cytoplasm
Subcellular location (Human Protein Atlas): Cytoplasmic bodies; Cytosol
Pathways (Reactome):
Immune System: AMPK-induced ERAD and lysosome mediated degradation of PD-L1(CD274); Activation of NF-kappaB in B cells; Antigen processing: Ubiquitination & Proteasome degradation; CLEC7A (Dectin-1) signaling; Cross-presentation of soluble exogenous antigens (endosomes); Dectin-1 mediated noncanonical NF-kB signaling; Downstream TCR signaling; ER-Phagosome pathway; FCERI mediated NF-kB activation; GSK3B-mediated proteasomal degradation of PD-L1(CD274); Interleukin-1 signaling; NIK-->noncanonical NF-kB signaling; Neutrophil degranulation; SPOP-mediated proteasomal degradation of PD-L1(CD274); TNFR2 non-canonical NF-kB pathway
Cell Cycle: APC/C:Cdc20 mediated degradation of Securin; APC/C:Cdh1 mediated degradation of Cdc20 and other APC/C:Cdh1 targeted proteins in late mitosis/early G1; Autodegradation of Cdh1 by Cdh1:APC/C; Autodegradation of the E3 ubiquitin ligase COP1; Cdc20:Phospho-APC/C mediated degradation of Cyclin A; FBXL7 down-regulates AURKA during mitotic entry and in early mitosis; G2/M Checkpoints; SCF(Skp2)-mediated degradation of p27/p21; SCF-beta-TrCP mediated degradation of Emi1; Separation of Sister Chromatids; The role of GTSE1 in G2/M progression after G2 checkpoint; Ubiquitin-Mediated Degradation of Phosphorylated Cdc25A; Ubiquitin-dependent degradation of Cyclin D
Signal Transduction: Asymmetric localization of PCP proteins; Degradation of AXIN; Degradation of DVL; Degradation of GLI1 by the proteasome; Degradation of GLI2 by the proteasome; Degradation of beta-catenin by the destruction complex; GLI3 is processed to GLI3R by the proteasome; Hedgehog 'on' state; Hedgehog ligand biogenesis; MAPK6/MAPK4 signaling; Negative regulation of NOTCH4 signaling; Regulation of PTEN stability and activity
and 28 more pathways
Gene Ontology:
Molecular function: proteasome-activating activity; protein binding; ATP binding; ATP hydrolysis activity
Biological process: osteoblast differentiation; ubiquitin-dependent protein catabolic process; cellular response to type I interferon; positive regulation of proteasomal protein catabolic process; proteasomal protein catabolic process; proteasome-mediated ubiquitin-dependent protein catabolic process; regulation of proteasomal protein catabolic process; response to oxidative stress
Cellular component: cytoplasm; cytoplasmic ribonucleoprotein granule; cytosol; membrane; nucleus; proteasome complex; extracellular region; ficolin-1-rich granule lumen; nucleoplasm; P-body; proteasome accessory complex; secretory granule lumen; synaptic vesicle
Genetic constraint (gnomAD): Loss-of-function variants: 5 observed, 38.43 expected, observed/expected ratio (o/e) 0.13, 90% interval 0.067 to 0.27. The upper end of that interval is the gene's LOEUF score, 0.27, which puts it in group 1 of 6, group 1 being the genes least tolerant of losing a copy. Missense variants: 205 observed, 484.08 expected, observed/expected ratio (o/e) 0.42, 90% interval 0.38 to 0.47. Synonymous variants: 150 observed, 169.29 expected, observed/expected ratio (o/e) 0.89, 90% interval 0.77 to 1.01.
Homologues: Orthologues: chimpanzee PSMC2 (100% identical), macaque PSMC2 (100% identical), pig PSMC2 (100% identical), rabbit PSMC2 (100% identical), rat Psmc2 (100% identical), mouse Psmc2 (99% identical), guinea pig PSMC2 (99% identical), zebrafish psmc2 (99% identical), tropical clawed frog psmc2 (93% identical), Drosophila melanogaster Rpt1 (92% identical), dog PSMC2 (89% identical), Caenorhabditis elegans rpt-1 (86% identical). Paralogues in human: PSMC5 (41% identical), PSMC6 (41% identical), PSMC1 (39% identical), PSMC3 (36% identical), PSMC4 (34% identical).
Diseases named in the same sentence as PSMC2 in open-access papers:
PSMC2 is named in the same sentence as 50 diseases in open-access papers, as found by Europe PMC text mining. Sharing a sentence is not in itself a finding about the gene and the disease. The quoted sentences say what the papers report.
osteosarcoma (12 papers, 2017 to 2022). A usually aggressive malignant bone-forming mesenchymal neoplasm, predominantly affecting adolescents and young adults. "Herein, we proved proteasome is necessary for osteosarcoma growth as its inhibition or deficiency for PSMC2 would lead to similar defects in osteosarcoma biological function." (PMID 27888613, 2017). "As PSMC2 is a crucial element for proteasome assembly and functional performance, we deduced PSMC2 depletion causing biological defects in osteosarcoma cell might associate with disabled proteasome activity." (PMID 27888613, 2017). "There are other studies showing that PSMC2 plays an important role in a number of cancers, such as osteosarcoma, pancreatic cancer, and human alveolar soft tissue sarcoma." (PMID 35287689, 2022). "In the present study, inhibition of PSMC2 reduced cell proliferation and increased cell apoptosis, which is consistent with PSMC2 as an oncogene for osteosarcoma." (PMID 35287689, 2022). "PSMC2 was expressed highly in osteosarcoma patients; knockdown of PSMC2 reduced cell proliferation, migration, and increased apoptosis, which indicated that PSMC2 act as an oncogene for osteosarcoma." (PMID 34716318, 2021). "Recently, more and more attention has been paid on the biological functions of PSMC2 in the development and progression of human cancers such as pancreatic cancer and osteosarcoma." (PMID 34294689, 2021). "deepen the understanding of the role of PSMC2 in osteosarcoma through identifying it as the target of miR-630 in the promotion of cell proliferation, migration, invasion and correlation of poor prognosis." (PMID 33902600, 2021). "In osteosarcoma samples, PSMC2 was highly expressed, and after silencing PSMC2, osteosarcoma cell lines (SaoS-2 and MG-63) showed cell proliferation inhibition, cell cycle arrest, and increased apoptosis, these changes were further confirmed in nude mice." (PMID 32972417, 2020). "PSMC2 likely drives osteosarcoma via its regulation of cancer-related genes, including ITGA6, FN1, CCND1, CCNE2 and TGFβR210." (PMID 31598166, 2019). "To investigate the molecular tumorigenesis mechanisms of PSMC2; we have used whole-genome Affymetrix GeneChip analysis to explore the striking changes of cancer-related genes between normal osteosarcoma cells and PSMC2 knockdown cells." (PMID 27888613, 2017). "To further verify this issue, we used flow cytometry to analyze cell cycle and apoptosis in PSMC2 silenced osteosarcoma cells." (PMID 27888613, 2017). "Compared with normal osteosarcoma cells, the growth of osteosarcoma cells was significantly reduced after PSMC2-knockdown." (PMID 27888613, 2017). "Silencing PSMC2 by RNA interference in osteosarcoma cell lines (SaoS-2 and MG-63) would significantly suppress cell proliferation, enhance apoptosis, accelerate G2/M phase and/or S phase arrest, and decrease single cell colony formation." (PMID 27888613, 2017). "Using tissue microarray experiments, we showed that PSMC2 protein was detected in 16 (66.7%) osteosarcoma specimens and mainly showed positive expression in nucleus and cytoplasm." (PMID 27888613, 2017). "Unexpectedly, exogenously increased expression of PSMC2 would also inhibit proliferation and colony formation in osteosarcoma cells." (PMID 27888613, 2017). "Right armpit region of NOD/SCID nude mice was chosen to perform subcutaneous injection with osteosarcoma cells that were infected with either control or PSMC2 siRNA lentiviruses." (PMID 27888613, 2017). "Our data strongly supported that PSMC2 was greatly required for invasion and migration capability in SaoS-2 osteosarcoma cells." (PMID 27888613, 2017). "Current study was focused on elucidating the significance of PSMC2 on malignant behaviors in osteosarcoma including proliferation, apoptosis, colony formation, migration as well as invasion." (PMID 27888613, 2017). "Osteosarcoma xenograft mouse models strongly supported the critical role of PSMC2 expression for in vivo tumorigenesis in nude mice." (PMID 27888613, 2017).
osteosarcoma (continued). "Giemsa staining was performed to explore the impacts of PSMC2 silence on colony forming in two different osteosarcoma cell lines with the fifteenth day of cell cultures." (PMID 27888613, 2017). "Here, we presented the silence of PSMC2 would effectively suppress osteosarcoma though TGFβR2 expression was reduced by PSMC2 knockdown." (PMID 27888613, 2017). "To study the expression of PSMC2 in osteosarcoma, we designed and screened a panel of tissue microarrays including 24 osteosarcoma samples and 5 normal bone samples." (PMID 27888613, 2017). "Overall, the observation above indicated exogenous enhanced PSMC2 expression applied less power on osteosarcoma proliferation and colony forming." (PMID 27888613, 2017). "Using tests of wound-healing assay and transwell migration, a positive correlation between PSMC2 expression and osteosarcoma metastasis had also been demonstrated." (PMID 27888613, 2017). "A positive correlation between PSMC2 expression and osteosarcoma metastasis was found in this study." (PMID 27888613, 2017). "Silencing of PSMC2 was able to inhibit osteosarcoma cell motility, invasion as well as tumorigenicity in nude mice." (PMID 27888613, 2017). "The high protein levels of PSMC2 in osteosarcoma samples were identified by tissue microarrays analysis." (PMID 27888613, 2017). "The cell colony numbers were quantified and demonstrated PSMC2-knockdown was efficiently inhibiting osteosarcoma cell colony formation." (PMID 27888613, 2017). "Besides, PSMC2 facilitated the proliferation and migration of osteosarcoma cells, and PSMC2 knockdown inhibited pancreatic cancer cell proliferation and induced apoptosis." (PMID 35256584, 2022). "Previous work has proved that PSMC2 itself or as the downstream target of miR-630 could regulate osteosarcoma cells proliferation, apoptosis and migration." (PMID 34244472, 2021). "Furthermore, another report further provided a deeper understanding of the relationship between PSMC2 and osteosarcoma based on the result that miR-630 promoted osteosarcoma cell proliferation, migration, and invasion by targeting PSMC2." (PMID 34413286, 2021). "Moreover, the role of PSMC2 in the development and progression of osteosarcoma has also been revealed as a tumor promotor." (PMID 33902600, 2021). "PSMC2 also expressed highly in osteosarcoma samples, as determined by tissue microarrays analysis." (PMID 31598166, 2019). "Our data suggested that PSMC2 may work as an oncogene for osteosarcoma and that inhibition of PSMC2 may be a therapeutic strategy for osteosarcoma treatment." (PMID 27888613, 2017). "However, the expressional correlation and functional importance of PSMC2 in osteosarcoma is still unclear." (PMID 27888613, 2017). "Herein, we may suggest that overexpressing PSMC2 may destroy malignant features and only partial expression of PSMC2 is an actual situation in the osteosarcoma cells." (PMID 27888613, 2017). "Taken together, PSMC2 could potently facilitate tumorigenesis and invasion in many respects throughout the progression of osteosarcoma." (PMID 27888613, 2017). "In summary, these results revealed that high levels of PSMC2 expression might be related to osteosarcoma development as well as serve as a marker for osteosarcoma diagnosis." (PMID 27888613, 2017). "Subsequently, we attempted to evaluate whether silencing PSMC2 in osteosarcoma would have an effect on tumor migration and invasion." (PMID 27888613, 2017). "Therefore, we carried out an elaborate research to explore the correlation of PSMC2 with human osteosarcoma." (PMID 27888613, 2017). "Furthermore, we found the necessary function of PSMC2 in osteosarcoma cell proliferation, apoptosis, colony forming, migration, invasion and tumorigenesis via loss-of-functional studies." (PMID 27888613, 2017). "Compared with osteosarcoma samples, PSMC2 expression was much less in normal bone samples." (PMID 27888613, 2017).
osteosarcoma (continued). "Furthermore, significantly reduced invasive ability was also witnessed in SaoS-2 osteosarcoma cells upon PSMC2 knockdown determined by a transwell based invasion assay." (PMID 27888613, 2017). "GO analysis indicated marked alterations between the control and PSMC2 knockdown osteosarcoma." (PMID 27888613, 2017). "This study verified the hypothesis that PSMC2 was high-expressed in human osteosarcoma and promoted tumorigenesis." (PMID 27888613, 2017). "66.7% osteosarcoma samples were with high expression of PSMC2." (PMID 27888613, 2017). "We thought that silencing PSMC2 might lead to an extensive and intricate chaos of cell cycle in osteosarcoma cells." (PMID 27888613, 2017). "The correlation of the PSMC2 expression and malignance degree of osteosarcoma needs further study." (PMID 27888613, 2017). "Interestingly, this partial expression of PSMC2 in osteosarcoma is still stronger than the expression of PSMC2 in normal tissue according to the results of our tissue microarray." (PMID 27888613, 2017). "Finally, we selected SaoS-2 and MG-63 cell lines for subsequent studies as their moderate levels of endogenous PSMC2 would be better to represent the expression of PSMC2 in primary human osteosarcoma tissues." (PMID 27888613, 2017). "Moreover, silencing of PSMC2 induced osteosarcoma cells arrest in G2/M and S phases as well as significantly increased apoptosis." (PMID 27888613, 2017). "Therefore, the finding of this study provided the new insight into the mechanism how PSMC2 contribute to osteosarcoma malignancy and further suggested PSMC2 might serve as an attractive potential therapeutic target drug target for osteosarcoma treatment." (PMID 27888613, 2017). "Consequently, knockdown of PSMC2 expression in SaoS-2 osteosarcoma cells and MG-63 osteosarcoma cells was ready to suppress cell growth rate determined by 3-(4,5-dimethyl-2-thiazolyl)-2,5-diphenyl-2-H-tetrazolium bromide (MTT) and fluorescence microscope during five-day cultures." (PMID 27888613, 2017). "Moreover, the result of overexpressing PSMC2 in osteosarcoma cells is still secret." (PMID 27888613, 2017). "To demonstrate the expression levels of PSMC2 in different osteosarcoma cell lines, we used real time-PCR and western blotting to verify that PSMC2 was ubiquitously expressed in SaoS-2, MG-63, U-2OS and HOS osteosarcoma cell lines." (PMID 27888613, 2017). "Nevertheless, more extensive and systematic researches on the functional roles of PSMC2 in osteosarcoma are still lacking." (PMID 27888613, 2017). "Here, we described the effect of PSMC2 in osteosarcoma neoplasm occurrence, growth and metastasis, which have never been reported in osteosarcoma." (PMID 27888613, 2017). "Growing evidence showed that proteasome 26 S subunit ATPase 2 (PSMC2) was able to promote tumor progression as a functional gene among several types of human tumors, including ovarian cancer, colorectal cancer (CC), osteosarcoma, pancreatic cancer, and hepatocellular carcinoma." (PMID 34716318, 2021).